OR1L6 (olfactory receptor family 1 subfamily L member 6)
Description:
Odorant receptor.
Synonyms: OR1L7; HG16; OR9-30
Tractability: Antibody: UniProt places it where antibodies can reach, with medium confidence; UniProt predicts a signal peptide or a membrane-spanning region; its Gene Ontology location is reachable by antibodies, with medium confidence.
Gene: Protein-coding gene on chromosome 9 (122,742,303 to 122,750,783, forward strand). Ensembl gene ENSG00000171459.
Subcellular location: Cell membrane
Pathways (Reactome):
Sensory Perception: Expression and translocation of olfactory receptors
Gene Ontology:
Molecular function: olfactory receptor activity; G protein-coupled receptor activity
Biological process: signal transduction; detection of chemical stimulus involved in sensory perception of smell; G protein-coupled receptor signaling pathway
Cellular component: plasma membrane; membrane
Genetic constraint (gnomAD): Loss-of-function variants: 11 observed, 8.87 expected, observed/expected ratio (o/e) 1.24, 90% interval 0.77 to 1.85. That is too few expected variants to judge how well the gene tolerates losing a copy. Missense variants: 291 observed, 355.34 expected, observed/expected ratio (o/e) 0.82, 90% interval 0.74 to 0.9. Synonymous variants: 114 observed, 135.5 expected, observed/expected ratio (o/e) 0.84, 90% interval 0.72 to 0.98.
Homologues: Orthologues: chimpanzee OR1L6 (96% identical), dog OR1L6 (86% identical). Paralogues in human: OR1L4 (94% identical), OR1L1 (68% identical), OR1L3 (66% identical), OR1L8 (61% identical), OR1F1 (55% identical), OR7C1 (54% identical), OR1N1 (54% identical), OR1N2 (53% identical), OR1K1 (53% identical), OR1M1 (53% identical), OR7C2 (53% identical), OR7D2 (52% identical), and 116 more.
Diseases named in the same sentence as OR1L6 in open-access papers:
OR1L6 is named in the same sentence as 1 disease in open-access papers, as found by Europe PMC text mining. Sharing a sentence is not in itself a finding about the gene and the disease. The quoted sentences say what the papers report.
tumor (1 paper, 2021). "In addition, our analyses identify a number of other poorly characterized genes (e.g., OR1L6 or OR4CC3) which may be high-confidence candidates to modulate tumor progression, proliferation, and/or metastasis." (PMID 34944895, 2021).